Y_RNA (Y RNA )
Gene: Miscellaneous RNA gene on chromosome X (136,816,477 to 136,816,574, reverse strand). Ensembl gene ENSG00000202279.
Homologues: Orthologues: chimpanzee Y_RNA (98% identical), macaque Y_RNA (93% identical), guinea pig Y_RNA (85% identical). Paralogues in human: Y_RNA (88% identical), Y_RNA (87% identical), Y_RNA (86% identical), RNY3 (85% identical), RNY3P14 (85% identical), Y_RNA (85% identical), RNY3P2 (84% identical), Y_RNA (84% identical), RNY3P1 (83% identical), Y_RNA (83% identical), RNY3P16 (82% identical), RNY3P4 (82% identical), and 95 more.